NLRC4 (NLR family CARD domain containing 4)
Diseases named in the same sentence as NLRC4 in open-access papers (continued):
Sharing a sentence is not in itself a finding about the gene and the disease.
streptococcal infection (1 paper, 2019). Any of the several infectious disorders caused by members of streptococcus, a genus of gram positive bacteria belonging to the family Streptococcaceae. "Although NLRP3 and AIM2 participate in IL-1β release by bmDCs and MΦ following infection by GBS and S. pneumoniae, the implication of NLRP1 and NLRC4 have not yet been described following streptococcal infection." (PMID 31262357, 2019).
uveitis (1 paper, 2024). An inflammatory process affecting a part of or the entire uvea. "Interestingly, uveitis was only present in members who also harbored c.928C>T in NLRC4." (PMID 38927735, 2024).
vaginal candidiasis (1 paper, 2025). "In this case, NLRC4 negatively regulates NLRP3 activation in epithelial cells and in a murine model of vaginal candidiasis." (PMID 41249509, 2025). "Conversely, in vaginal candidiasis, NLRP3 and NLRC4 were non-redundantly activated." (PMID 41249509, 2025).
infection (191 papers, 2009 to 2026). The state of being infected such as from the introduction of a foreign agent such as serum, vaccine, antigenic substance or organism. "NLRC4-deficient mice lack a crucial first line defence mechanism in IECs, resulting in accelerated infection kinetics and a rapid accumulation of pathogen-associated molecular patterns (PAMPs) that provoke broad immune responses such as TNF release." (PMID 41370284, 2025). "We compared S. TmWT or S. TmSPI2 infection (for 72 h) in streptomycin-pretreated NLRC4-deficient mice and their heterozygous littermates to observe the development of gut disease and changes in epithelial barrier integrity." (PMID 41370284, 2025). "Strikingly, the same pattern as in NLRC4-deficient mice was observed in CYBB-deficient mice: 72 h after S. TmWT infection the epithelial barrier collapsed while after 72 h of S. TmSPI2 infection the epithelial barrier remained intact." (PMID 41370284, 2025). "Consistent with the effects of IFN-γ neutralization, infected Ifngr1−/−Nlrc4−/−Casp11−/− mice experienced greater weight loss burdens than IFN-γ-sufficient Nlrc4−/−Casp11−/− animals 48h after infection." (PMID 40885187, 2025). "This appeared remarkably similar to the day 3 infection phenotypes previously seen in NAIP/NLRC4-deficient mice." (PMID 37988464, 2023). "Work in NLRC4-deficient mice had established that epithelial-dependent phenotypes are particularly prominent during the first day of the infection of streptomycin-pretreated mice, or the first few hours in enteroid infection models." (PMID 37988464, 2023). "Infection of NLRP3- or NLRC4-deficient bone marrow-derived macrophages (BMDMs) with Salmonella revealed that inhibition of Caspase-1 by GalE was dependent on the NLRP3 inflammasome." (PMID 35630356, 2022). "P. aeruginosa ExoU associates with mitochondria during infection, and the association involves NLRC4." (PMID 35130452, 2022). "Certain bacteria can survive intracellularly and can dampen the activation of NLRC4 inflammasomes, thus evading detection by the host immune system and causing severe infections." (PMID 34276697, 2021). "In further studies, the investigators showed that NLRC4 deficiency caused increased mortality after infection with Salmonella." (PMID 33808793, 2021). "It has been reported that the NLRC4 inflammasome can be triggered either by infection or by purified flagellin from mammalian pathogenic bacteria such as S. typhimurium, Legionella pneumophila, Pseudomonas aeruginosa, and Listeria monocytogenes." (PMID 34203170, 2021). "At 2 h postinfection, IL-1β and IL-18 production was reduced in both parental and NLRC4 KO THP-1 cells infected with the flagellin- or T3SS/flagellin-deficient strain in comparison with infection with wild-type S. Typhimurium." (PMID 33380493, 2021). "PAMP-primed cells activate NOD-like receptor (NLR) family CARD domain-containing protein 4 (NLRC4) upon detecting cytosolic flagellin during infection; this protein causes caspase 1 to release inflammatory cytokines like IL-1β and IL-18, and drives pyroptosis." (PMID 34203170, 2021). "Knockout (KO) of NLRC4 leads to loss of inflammasome activation at early time points during infection." (PMID 33380493, 2021). "Nlrc4-deficient mice showed increased susceptibility to infection with bacterial pathogens such as Salmonella typhimurium, which indicates that NLRC4 inflammasome confers innate immune protection against pathogenic bacteria." (PMID 33312172, 2020). "NLRP3 and NLRC4 together allow for the recognition of different danger signals from the same pathogenic infection." (PMID 29997616, 2018). "The observed defect in NLRC4 inflammasome activation was reproducible in vivo; Irf8−/− mice were more susceptible than WT mice to infection with S. Typhimurium or B. thailandensis." (PMID 31225480, 2018). "Accordingly, macrophages and mice deficient in Asc/Casp1/11-/- were more susceptible than Casp1/11-/- and as susceptible as Nlrc4-/- for the restriction of infection." (PMID 28771586, 2017).
infection (continued). "Infections performed with L. gratiana and L. micdadei indicated that Asc/Casp1/11-/- macrophages were as susceptible as Nlrc4-/-, whereas Casp1/11-/- cells were partially restrictive." (PMID 28771586, 2017). "In fact, NLRC4-/- BMDM were highly susceptible to infection despite secreting more TNF than WT BMDM in response to L. pneumophila infection, possibly due to increased bacterial burden or a failure to undergo pyroptosis." (PMID 27105352, 2016). "But 12 hours post infection NLRC4-deficient and wild-type macrophages displayed similar caspase activation and PARP cleavage." (PMID 24626296, 2014). "To further investigate the mechanisms responsible for caspase-1 activation by V. parahaemolyticus, we next examined caspase-1 activation in NLRP3- or NLRC4-deficient macrophages in response to infection with V. parahaemolyticus." (PMID 23357873, 2013). "We also observed that NLRC4-deficient animals have increased alveolar space inflammation at 72 h post-infection." (PMID 23937571, 2013). "Similar levels of LDH were released fromNLRP3, NLRC4 or ASC-deficient BMDMs as compared wild-type macrophages afterYp-YopJKIM infection." (PMID 21533069, 2011). "A consequence of caspase-1 activation in macrophages following infection by NLRC4-activating pathogenic bacteria (see Section 3.1) is a rapid, and caspase-1-dependent cell death called pyroptosis." (PMID 22019906, 2011). "Remarkably, despite the abundance of IL-1β and IL-18, Nlrc4-/- mice were dramatically more susceptible to melioidosis than WT mice, rapidly succumbed to the infection, and had very high organ's bacteria burden and worst neutrophilic lung inflammation." (PMID 22241982, 2011). "Specifically, we asked whether severe gut inflammation in immune-deficient hosts (NLRC4- or CYBB-deficient) could still be triggered by infection with an attenuated strain, S. TmSPI2." (PMID 41370284, 2025). "Both GSDMD and NAIP/NLRC4 limit S.Tm loads in the deeper gut mucosal tissue, as well as in systemic organs, and prevent the loss of epithelial barrier integrity by 48 to 72 h of infection." (PMID 37988464, 2023). "To further investigate the mechanisms responsible for Caspase-1 activation by S. Enteritidis GalE protein, we monitored the activation of Caspase-1 in Nlrp3−/− and Nlrc4−/−-deficient BMDMs in response to infection with different mutant strains of S. Enteritidis." (PMID 35630356, 2022). "The data suggest that ExoU differentially affects NLRC4 inflammasome activation early in infection, causing a transient delay in caspase-1 release to the culture medium, whereas the effects of ExoU can be observed in enriched mito-MAM fractions at later time points." (PMID 35130452, 2022). "Studies are ongoing to examine mechanisms underlying ExoU-mediated inhibition of the NLRC4 activation during P. aeruginosa infection and to determine whether these observations translate to animal models of infection and, ultimately, to human cells." (PMID 35130452, 2022). "For example, the importance of the host’s response to flagellated microbes is evident in mice deficient in either TLR5 or NLRC4, which because of their inability to effectively detect flagellin are more susceptible to basal inflammation and infection by enteric pathogens." (PMID 35401545, 2022). "Similar to the importance of NLRC4 during infection with L. pneumophila, Nlrc4-deficient mice infected with other Legionella species, including L. micdadei, L. bozemanii, L. gratiana, and L. rubrilucens, are more susceptible and have increased bacterial burden compared with wildtype infected mice." (PMID 33494299, 2021). "Nlrc4-deficient mice have reduced inflammation and control the bacterial burden more successfully than wildtype infected mice do, highlighting the pathogenic role NLRC4 can play during infection." (PMID 33494299, 2021).
infection (continued). "However in a recent study using NLRC4 deficient mice, it has been shown the NLRC4 plays a protective role against infection with Citrobacter rodentium that is dependent on its expression in non-hematopoietic cells." (PMID 25071778, 2014). "However, LDH release from NLRC4-deficient cells was considerably decreased by infection with ΔtdhASΔh1, raising the possibility that some effectors encoded in the h1 region affect NLRP3-mediated LDH release in a caspase-1 activation-independent manner." (PMID 23357873, 2013). "However, during experimental infection mice deficient in NLRC4 are able to clear S. Typhimurium just as efficiently as control mice, suggesting the involvement of other inflammasomes." (PMID 23055923, 2012). "However, cell death associated with IL-1β release is not only dependent upon infection with NLRC4-activating pathogens." (PMID 22019906, 2011). "These reduced tissue loads may explain why NLRC4-deficient mice infected with S. TmSPI2 retained an intact epithelial barrier, showed no defects in regeneration capacity and overall lower histopathology scores than in S. TmWT infection." (PMID 41370284, 2025). "Casp1/11/8–/–Ripk3–/– mice, however, should lack the cell death pathways initiated by NLRC4 (via Caspase-1 or Caspase-8), Caspase-11, and TNFα, and our results above suggest that these mice might be highly susceptible to infection." (PMID 36645406, 2023). "This was shown in the examples of NAIP/NLRC4 or GSDMD (downstream of NLRC4 inflammasome; executer of pyroptotic cell death) deficiency, where failure to initiate timely epithelial immune responses resulted in increased pathogen loads and disruption of the epithelium at later stages of the infection." (PMID 37384776, 2023). "However, B6.Nlrc4–/– mice challenged with ΔospC3 S. flexneri were less susceptible to infection, exhibiting significantly less weight loss, a >10-fold decrease in IEC colonization, reduced cecum shrinkage, and a decrease in CXCL1 relative to WT-infected B6.Nlrc4–/– mice." (PMID 36645406, 2023). "NLRC4 protects the host against certain pathogens, such as Salmonella, Citrobacter or Legionella, but its activation may also be pathogenic by triggering strong inflammation during some infections, such as during Helicobacter infection." (PMID 33494299, 2021). "In contrast, in vivo infection of bone marrow chimera mice showed higher mucosal colonization in NLRC4 deficient recipient mice reconstituted with WT inflammatory cells than WT recipients reconstituted with Nlrc4-/- cells, which had similar levels of oral mucosal infection as WT controls." (PMID 22174673, 2011). "Infection with the mT3Sf::OspF strain also suppressed NLRC4-dependent IL-1β processing induced by the synthetic NAIP–NLRC4 agonist NeedleTox." (PMID 41533441, 2026). "Transcriptional analysis further revealed that infection of Nlrc4-/- organoids with invasive or non-invasive S. flexneri resulted in the downregulation of inflammatory signaling." (PMID 41871150, 2026). "In response to the infection, IL-22 cytokine production is induced and activates NLRC4, which then sustains the production of the IL-1 receptor antagonist IL-1Ra, which acts as a suppressor of inflammasome activity." (PMID 41249509, 2025). "In our earlier experiments with immune-deficient mice (NLRC4- and CYBB-deficient), we found that TTSS-2 virulence accelerated mucosal histopathology during the first 72h of infection." (PMID 41370284, 2025). "Further studies need to be performed to understand the precise role of NLRC4 and how different inflammasomes can interact with each other to either induce a protective response or promote infection." (PMID 41249509, 2025). "The significance of NLCR4/NAIP has been demonstrated in Nlrc4−/− mice, which show 50-fold higher S. Tm loads in the caecum tissue compared to Nlrc4+/− littermate controls at 18 h post infection." (PMID 40796289, 2025).
infection (continued). "A similar reduction was observed during infection with the ΔmsbB mutant, suggesting that ST-induced coagulation is primarily mediated through NLRC4, and that msbB deletion dampens this signaling." (PMID 41304196, 2025). "GSDMD is a downstream effector of NLRC4 and, like NLRC4-deficiency, GSDMD-deficiency in mice leads to the collapse of the epithelial barrier after 72 h of S. TmWT infection." (PMID 41370284, 2025). "Continued, pronounced SPI-1-dependent assault on the epithelium appears to drive less regulated IEC extrusion in later stages of infection, which is thought to be NLRC4-independent and further exacerbated by TNF." (PMID 41370284, 2025). "Strikingly, all Ifngr1−/−Nlrc4−/−Casp11−/− mice reached predefined humane endpoints (e.g., <75% starting body weight, severe signs of morbidity) 72h post-infection, while all Nlrc4−/−Casp11−/− mice survived and regained their initial weight." (PMID 40885187, 2025). "Consistent with our findings that ST induces pyroptosis in murine macrophages, recent studies have confirmed NLRC4 activation in human macrophages upon ST infection." (PMID 41304196, 2025). "To identify the inflammasome sensors responsible for the recognition of A. baumannii, we inoculated WT BMDMs with A. baumannii 1605 and measured Nlrc4, Aim2, Nlrp3 and Caspase-11 transcript levels in cell lysates at 6- and 12-hours post infection." (PMID 39533032, 2024). "Despite this strong relevance in host immune response to infection and inflammatory diseases, the detailed structural basis of the NLRC4 inflammasome assembly and pathogen sensing in humans was lacking." (PMID 38177670, 2024). "A decrease in NLRC4 expression can heighten infection risks, disrupt gut microbiota balance, and lead to inflammatory response dysregulation and immune system impairment." (PMID 39292002, 2024). "Together, these data suggest that IRF1 is dispensable for inflammasome activation and cell death in response to infection with both NLRC4 inflammasome–activating pathogens as well as caspase-11–activating pathogens." (PMID 37557956, 2023). "The host detects pathogen invasion through cytosolic PRRs such as NLRP3, AIM2, and NLRC4, and induces immune responses to resistant infection through the inflammasome assembly." (PMID 38136879, 2023). "We also found that Nlrc4+/–Il1r1–/– mice largely phenocopy Nlrc4+/–Il1r1+/– mice and are resistant to infection." (PMID 36645406, 2023). "In response to the infection of Lm-pyro L. monocytogenes strain, the activation of inflammasome similar to the murine NAIP5/NLRC4 inflammasome in zebrafish induces macrophage recruitment to infection sites." (PMID 36875130, 2023). "In both B6.Nlrc4–/–Casp11–/– and 129.Nlrc4–/– mice, TNFα neutralization led to a striking increase in severity of infection and a 10-fold increase in bacterial colonization of the intestinal epithelium." (PMID 36645406, 2023). "We next assessed viability of WT, Nlrc4–/–, Casp1–/–, and Gsdmd–/– BMMs during FliCON infection using a lactate dehydrogenase (LDH) assay." (PMID 38055781, 2023). "The essential role of the NLRC4 inflammasome is to maintain normal innate immunity during infection." (PMID 37515138, 2023). "The inflammasome molecules AIM2, NLRP3, NLRP6 and NLR Family Apoptosis Inhibitory Protein (NAIP)/NLRC4 were reported to play important roles in epithelial cells by protecting against infection and maintaining tissue homoeostasis." (PMID 37365163, 2023). "To create an infection model where the majority of NLRC4 activation arises only from the engineered FliCON, we used a flgB mutant background to ablate endogenous flagellin expression and used a competitive index vs vector control bacteria." (PMID 38055781, 2023). "NLRC4 inflammasome can still detect Salmonella with suppressed flagellin/SPI-1 expression at late times post-infection." (PMID 37155697, 2023).